BRAF (B-Raf proto-oncogene, serine/threonine kinase)
Diseases named in the same sentence as BRAF in open-access papers (continued):
Sharing a sentence is not in itself a finding about the gene and the disease.
tumor (continued). "It was also suggested that BRAF mutation in PTC is a late sub-clonal event, and the same tumor can contain epithelial cells with wild type BRAF as well as cells with mutant BRAF." (PMID 31810221, 2019). "In a BRAF V600E mutated brainstem ganglioglioma, tumor regrowth was observed after withdrawal of vemurafenib." (PMID 31181803, 2019). "Only 10 (7.5%) patients harbored MSI; five of them had BRAF mutation in both tumor tissue and plasma, one had a mutation only in tissue, and one had mutation only in plasma." (PMID 31319569, 2019). "Although high concordance rates have been described in some studies, others do report heterogeneity in RAS and BRAF mutations ranging from 5% to 32% between the primary tumor and metastatic sites." (PMID 31350822, 2019). "Mutations in RAS (exons 2–4) and particularly BRAF (V600E) in the tumour cells are associated with impaired prognosis, and mutation status is routinely used in the clinical management of patients with mCRC." (PMID 29872151, 2018). "Complete tumor staging information should be assessed, including pathological features of the primary tumor and any involved lymph nodes, as well as BRAF mutation testing." (PMID 29848375, 2018). "Only rarely BRAF V600E mutation occurs in conjunction with a BRAF/KIAA1549 rearrangement in the same tumor." (PMID 30558563, 2018). "BRAF-IR PTCs showed enrichment of tumor infiltrating immune cells, tall cell variant PTC, and shorter recurrence-free survival compared to BRAF-ID PTCs." (PMID 30563160, 2018). "BRAF mutations were as likely to first appear in metastases derived from WT tumors as they were to be found in the primary tumor that subsequently had WT metastases." (PMID 29148538, 2018). "Six BRAF mutated human tumor cell lines CRL5885 (G466 V), WM3629 (D594G), WM3670 (G469E), MDAMB231 (G464 V), CRL5922 (L597 V) and A375 (V600E as control) were investigated." (PMID 29739364, 2018). "Two of these patients, one with NSCLC and one with a neuroendocrine tumor, exhibited persistent memory T cell responses to neoantigens derived from mutations in the oncogenic BRAF and tumor-suppressor PTCH1 genes, respectively." (PMID 30400822, 2018). "They found that KRAS and BRAF are mutually exclusive in earlier tumor stages (Tis and T1), but concomitant mutations were detectable in higher tumor stages and correlated with increased depth of invasion." (PMID 30234115, 2018). "We performed sequencing on the samples that BRAF mutation was detected by our assay using the GeneReader next generation sequencing system and GeneRead QIAact Actionable Insights Tumor Panel." (PMID 29879227, 2018). "Based on the tumor cell fraction and the variant allelic frequency we estimated that at least in cases N27 and N4 the BRAF mutations were clonal (VAF 42% and 20%, respectively)." (PMID 29556019, 2018). "Genetic mutation analysis of the tumor should also be performed with special emphasis on identifying mutations in BRAF." (PMID 29848375, 2018). "Cancers with BRAF mutation are closely related to tumor location and lower survival, especially for those together with MSI-low (MSI-L) or microsatellite stable (MSS)." (PMID 29643917, 2018). "In conclusion, based on our experience we suggest considering LB for patients who have not had TB or have insufficient tissue to determine the presence of KRAS/NRAS/BRAF mutations, especially in the context of high tumor burden prior to therapy." (PMID 30705875, 2018). "In pooled multivariate analyses of PRIME and PEAK using the 45-month cut-off, panitumumab treatment again predicted long-term survival, along with low- and medium-risk Köhne score, BRAF WT status and left-sided primary tumour location." (PMID 30013091, 2018).
tumor (continued). "Tumor tissue preservation is increasingly a priority as biomarker testing, such as BRAF mutational analysis, PD-L1 immunohistochemistry and this GEP test, are integrated in patient management decisions." (PMID 29433548, 2018). "The data showed that the prognostic information from elevated levels of CA 19-9 differed depending on the RAS and BRAF mutation status of the tumour, with a statistically significant interaction in adjusted analyses (P = 0.003)." (PMID 29872151, 2018). "Of the 32 tumour samples analysed, at least one mutation was known to be present with 94% of the samples harbouring a mutation in BRAF V600." (PMID 29986670, 2018). "Another study suggested that the prognostic significance of BRAF mutations depends on the microsatellite instability of the tumor." (PMID 30479693, 2018). "A study showed that dietary fat promotes mutated BRAF (BRAF V600E) tumor growth and that hypolipidemic agents inhibit BRAF V600E tumor growth." (PMID 30573851, 2018). "This BRAF mutation was detected (i) in the primary tumor, (ii) in all the CTC lines, (iii) the lymph node metastasis, and also (iv) in tumor xenografts obtained by injection of CTC-MCC-41 cells." (PMID 30374140, 2018). "Nowadays, the national comprehensive cancer network (NCCN) recommends tumor tissue genotyped for Ras-BRAF mutations in suspected or metastatic rectal cancers in order to tailor therapy and to confer – if any – benefit to patients." (PMID 30263096, 2018). "When the results of KRAS/BRAF tissue analysis by ddPCR were taken into account, 59 patients were found to have mutant tumours for either KRAS or BRAF (mutations being detected in 38 cases by standard PCR-based techniques while in 21 cases by ddPCR)." (PMID 29362371, 2018). "In mismatch repair-deficient (dMMR) tumours, BRAF mutations are associated with a good prognosis, whereas in MMR-competent tumours, they are detrimental." (PMID 29988110, 2018). "Here, we found that the frequency of KRAS and BRAF mutations was higher in the lung metastatic tumours than that in the liver metastatic tumours." (PMID 30171333, 2018). "We also identified a trend towards enhanced OS from adjuvant bevacizumab limited only to the subgroup of patients with BRAF mutated tumours." (PMID 30010756, 2018). "The potential use of immunotherapy was exemplified by an exceptional response observed upon treatment with Vemurafenib (BRAFV600E inhibitor) and Nivolumab (human IgG4 anti-monoclonal PD-1 antibody) for tumor harboring BRAF mutation and PDL-1 positivity." (PMID 30352606, 2018). "Only 3 patients (3%) were found to have BRAF mutant tumours (in 2 cases the mutation was detected in paired samples while in 1 case in the pre-treatment biopsy only)." (PMID 29362371, 2018). "We observed abnormalities in 18/20 (90%) of Group 1 tumours, of which 13 (65%) possessed a BRAF-V600E mutation." (PMID 29058119, 2018). "A retrospective analysis of BRAF mutations in prospectively collected tumor blocks from patients enrolled in the PETACC-8 trial demonstrated that the BRAFV600E mutation was not prognostic in the entire cohort." (PMID 30479693, 2018). "Among the most clinically relevant studies, Tsai and collaborators proved the anti-tumor potential of the mutated-BRAF selective inhibitor (PLX4720) in BRAFV600E-dependent tumor xenograft models, inducing a significant tumor growth delay and even regression." (PMID 29534457, 2018). "CtDNA was detectable (average MAF = 7.4%, range 0.03–32.8; median mutant molecules/mL = 26.24, interquartile range of 8.42–1162.0) in 22 of 27 (81%) with BRAF mutations, in whom the average tumor burden was 379 mm (range 7–4278)." (PMID 30113761, 2018).
tumor (continued). "In sporadic CRC, patients with mismatch repair (MMR)-deficient (dMMR) tumours harbouring BRAF mutations have an improved survival." (PMID 29988110, 2018). "We classified tumours into five different subtypes based on BRAF and KRAS mutation, CIMP status, and MSI." (PMID 30188916, 2018). "In patients whose tumour harboured a BRAF V600 mutation, one patient received one dose of pembrolizumab on the compassionate program while awaiting results of BRAF molecular testing." (PMID 29610684, 2018). "MMR-competent stage III tumours harbouring BRAF mutations have an improved prognosis when strong nuclear phosphorylation of both ERK and p38MAPK is present." (PMID 29988110, 2018). "Increased expression levels of MIR146B were related with advanced stage, tumor size, extrathyroidal extension, and BRAF mutation, as previously reported." (PMID 30454026, 2018). "The BRAF(p.V600E) point mutation, e.g., is found in a wide range of malignant and benign neoplastic diseases in many organ systems." (PMID 29441349, 2018). "Taken together, we found that the MEK inhibitor improved tumor regression in the presence of BRAF and MEK1 mutations." (PMID 29896883, 2018). "Samples of group C compared with those of group A are prevalently localized on the right colon (p < 0.0001), are associated with medullary histological type (p < 0.0001), G3 tumor grade (p < 0.0001), BRAF mutation (p = 0.001) and MSI status (p < 0.0001)." (PMID 29492219, 2018). "This variant, as other mutations in the BRAF kinase domain, leads to a continuous stimulation of cell proliferation and tumor growth through constitutive phosphorylation of ERK." (PMID 29492214, 2018). "On the basis of OncoPanel testing of her tumor from her recurrence surgery, which revealed a BRAF c.1799T>A (p.V600E) mutation, she started vemurafenib at 480 mg twice daily, which was dose reduced to 240 mg twice daily because of cutaneous toxicity." (PMID 30828692, 2018). "Regarding immunohistochemistry, 12/211 of the cases demonstrated NIS in the membrane of tumor cells, those cases showed variable outcomes concerning therapy success, prognosis and all but one were wild type for BRAF, NRAS and TERTp mutations." (PMID 29298843, 2018). "We demonstrated detection limits superior to those provided by many current technologies in the detection of RAS and BRAF gene superfamily mutations, a level of sensitivity compatible with the analysis of cell free circulating tumor DNA in liquid biopsy." (PMID 30562355, 2018). "Nevertheless, our data is important to consider in the aetiology of cancers expressing N-terminally deleted forms of BRAF including splice variants that arise in tumours with acquired resistance to the BRAF inhibitor vemurafenib." (PMID 30603699, 2018). "In the tumor from one patient, who was positive for the BRAF V600E mutation, a known polymorphism within TERTp was found (rs2735943; −100 C->T)." (PMID 30200646, 2018). "Enhanced oxidative stress and DNA damage have linked not only with a more aggressive tumour phenotype, but also with resistance to BRAF target drugs, such as vemurafenib." (PMID 29492238, 2018). "They found that the prognostic impact of CDX2 depended on the MMR and BRAF mutational status of these tumours." (PMID 30511046, 2018). "In almost all resistant tumours the MAPK pathway is reactivated either via activating mutations or amplification in BRAF, MEK1/2 or NRAS or via the transcriptomic upregulation of receptor tyrosine kinases, including PDGFRß and c-MET2,16." (PMID 30237495, 2018). "This occurs due to the paradoxical activation of ERK signaling in tumor cells with wild-type BRAF or the ones that harbor RAS and BRAF mutations mutually." (PMID 29455659, 2018).
tumor (continued). "Ten of 53 patients (19%) had discordant tumor samples that harbored both BRAF WT and mutation-positive metastases." (PMID 29148538, 2018). "In order to identify a potential target for an experimental salvage therapy, mutational tumor analysis showed a BRAF V600E mutation." (PMID 29621181, 2018). "Right-sided tumours more often exhibit BRAF-mutations, microsatellite instability, CpG island methylator phenotype, mucinous differentiation and serrated pathway signature." (PMID 29298682, 2018). "The use of tumor tissue RNA instead of DNA as the starting material enabled us to correlate the mRNA expression of BRAF V600E mutations directly with SPINK1 mRNA expression level analyzed by qPCR from the same tumor samples." (PMID 29193645, 2018). "It is due to the presence of heterogenous cell populations within one patient's tumor, e.g., cell clones harboring BRAF mutations and others comprising NRAS mutations." (PMID 30237393, 2018). "Anti-PD-1 was less effective in BRAF-mutated cases as a majority of patients presented aggressive tumor evolution after BRAFi discontinuation." (PMID 29970025, 2018). "Specifically, among tumor-testing strategies, IHC followed by BRAF mutation testing was preferred, with an ICER of 34,345 €/LYG." (PMID 29386984, 2018). "We observed abnormalities in 13/26 (54%) Group 1 tumours, of which 12 (46%) possessed a BRAF-V600E mutation." (PMID 29058119, 2018). "In the analysis of the BRAF exon 15 mutation in primary tumour site, 23 of the 296 female patients with CRC (7.8%) showed the presence of the BRAF mutation and all of them carried the V600E mutation." (PMID 29662660, 2018). "Unlike the well-defined molecular classes of IDH-mutant tumours, the V600E point mutation in the BRAF gene occurs only in a subset of these nosological tumour entities." (PMID 29098416, 2018). "Before anti-PD-1 first administration, poor PS (≥1: 80.5% vs. 39.4%, p < 0.001), brain metastasis (61.0% vs. 18.2%, p < 0.001), and important tumor burden (> 3 metastatic sites: 48.8% vs. 24.2%; p = 0.04) were significantly higher in BRAF-mutated patients." (PMID 29970025, 2018). "For example, KIAA1549‐BRAF fusions are more common in posterior fossa tumours (up to 90%), compared to supratentorial tumours (33–59%), and BRAF V600E mutations are more frequent in supratentorial tumours (~ 18%) than those in the posterior fossa (~ 3%)." (PMID 28388012, 2018). "We analyzed 14 biomarkers and 17 SNPs in prediagnostic blood and determined KRAS and BRAF mutation status in tumor tissue." (PMID 29694444, 2018). "In all five patients, additional MAPK-activating alterations, including NRAS and MEK2 mutations, were acquired in the matched tumours progressing on BRAF inhibitor monotherapy or BRAF/MEK inhibitor combination treatment." (PMID 30237495, 2018). "The tumor remained grade 2 and was found to harbor the V600E BRAF mutation as well as MGMT promoter methylation." (PMID 29708404, 2018). "The results of this study showed that KRAS and NRAS mutataions are usually present in the large majority of tumor cells, whereas BRAF and PIK3CA mutations often affect a limited, subclonal fraction of tumor cells." (PMID 29652830, 2018). "The cobas 4800 BRAF V600 mutation test and the THxID-BRAF kit both use RT-PCR to amplify and detect the mutant DNA sequence in a tumor sample." (PMID 29148538, 2018). "There was some evidence to suggest that patients with NRAS mutant tumours compared to those with BRAF/NRAS wild-type tumours had an increased risk of developing disease recurrence following a negative SLNB (aHR = 1.72, 95% CI 0.80–3.67, p = 0.16)." (PMID 29755118, 2018). "The tumor from this patient had fewer than 30 somatic mutations and the BRAF V600E specific CD4+ T cell response was correlated with robust and persistent CD8+ T cell responses to multiple self–antigens." (PMID 30400835, 2018).
tumor (continued). "It has been shown that this assay was able to detect artificial tumor blends with 5% mutant BRAF alleles." (PMID 29879227, 2018). "The KRAS mutation analysis showed a 96% concordance with tumor tissue and plasma cfDNA while the BRAF mutation analysis showed a 100% concordance." (PMID 30373199, 2018). "This study shows evidences for the clinical use of these drugs for neoplasias harboring other BRAF mutations." (PMID 29455659, 2018). "There were 477 patients in the MMP cohort who underwent SLNB and had BRAF/NRAS mutation testing of their tumour from 2010–2015." (PMID 29755118, 2018). "These include proteins related to cell adhesion, apoptosis regulation, cell cycle, cell proliferation, BRAF V600 mutations, tumor front, angiogenesis, bone remodeling, and the ECM." (PMID 29850393, 2018). "When BRAF and NRAS mutation were analysed separately, patients with BRAF mutant tumours compared to patients with BRAF/NRAS wild-type tumours had increased risk of developing disease recurrence following a negative SLNB (aHR 2.07, 95% CI 1.05–4.09, p = 0.04)." (PMID 29755118, 2018). "Most patients (94%) had their tumor molecularly genotyped, and abnormalities (e.g., mutations, fusions, and rearrangements) in BRAF, KRAS, and MEK were documented." (PMID 29603015, 2018). "The genetic profile of HT-29 cells represents the KRAS and NRAS wild-type tumor subtype, but includes the activating V600E mutation in the BRAF gene." (PMID 30410004, 2018). "There are also other factors unaccounted for in these analyses (e.g. primary tumour location, BRAF mutation status, etc.), which are also likely to impact on survival outcomes." (PMID 29080924, 2018). "In the multivariate analysis we tested the prognostic value of RAS mutation in the serum and the combination of BRAF mutation in the serum and pMMR in the tumor against conventional prognostic factors and they both remained statistically significant." (PMID 28378527, 2017). "Next, there is still discussion about the effect of the oncogenic BRAF (V600E) mutation on autophagy dependency of tumour cells." (PMID 29225688, 2017). "Molecularly, xenograft cells with homozygous deletion of CDKN2A shifted from disomy chromosome 9 to trisomy chromosome 9; and BRAF V600E mutation allele frequency increased (from 28% in patient tumor to 67% in passage III xenografts)." (PMID 29152094, 2017). "Our long-term follow-up of in vivo growth of IC-3635PXA tumors revealed a clear enrichment of BRAF V600E mutation frequency and detected a novel a shift of diploid chromosome 9 to trisomy 9 in tumor cells bearing CDKN2A deletion." (PMID 29152094, 2017). "In fact, the list of the induced genes is remarkably similar to that observed in tumours with a mutated BRAF." (PMID 28651004, 2017). "In this study, we found that patients with a RAS, PIK3CA, or BRAF tumor mutation had a lower ORR than patients with tumors that did not carry these mutations, although this difference was not statistically significant." (PMID 28068936, 2017). "The BRAF oncogene is the most commonly mutated gene in human cutaneous melanomas, and this oncogene also drives tumor cell proliferation." (PMID 28753606, 2017). "A RAS or BRAF mutation both in the serum and in the tumor resulted in significantly worse OS (P = 0.012) and DFS (P = 0.026) compared to a mutation in the tumor only." (PMID 28378527, 2017). "Consistent with previous studies CIMP-H tumours were enriched (21/26, 81%, p value =0.016 using Welch t test) in the proximal colon and were associated with BRAF (V600E) mutations (14/26, 54%, p value <0.001)." (PMID 28351398, 2017). "In vitro studies demonstrated a tendency toward sensitivity to MEK inhibitors in tumor cell lines harboring KRAS or BRAF mutations." (PMID 29296181, 2017). "High cytoplasmic RBM3 expression was significantly associated with age <75 years, BRAF wild type tumour, secondary surgery and irinotecan based treatment." (PMID 28800641, 2017).